NUDT1 (nudix hydrolase 1)
Diseases named in the same sentence as NUDT1 in open-access papers (continued):
Sharing a sentence is not in itself a finding about the gene and the disease.
tumor (continued). "The decreased expression of HIF2α inhibits the expression of NUDT1 at the transcriptional level and causes the degradation of SIRT3 to accelerate, which cause an increase in tumour cell ROS and oxidative stress levels, thereby inhibits the progress of ccRCC." (PMID 34841698, 2021). "At the same time, small animal live imaging based on tail vein metastases in nude mice showed that knocking down NUDT1 can significantly reduce the level of tumour metastasis." (PMID 34841698, 2021). "HIF2α can directly transcriptionally activate the expression of NUDT1, reduce the biological impact of oxidative stress on tumour cells and promote tumour growth and metastasis." (PMID 34841698, 2021). "It is worth noting that the screening of NUDT1 is based on oxidative stress, and at the same time, oxidative stress plays an essential role in tumour progression." (PMID 34841698, 2021). "The presence of strong oxidant driver will eliminate the redundant function of NUDT1 inhibitors on tumours." (PMID 34841698, 2021). "Western blot results of xenograft tumour tissues showed that NUDT1 silencing led to a decrease in NRF2 levels in the body." (PMID 34841698, 2021). "Analysis experiments based on the growth rate of tumour cells suggest that knocking down NUDT1 can significantly inhibit the proliferation rate of ccRCC cell lines, while overexpression of NUDT1 can have the opposite result." (PMID 34841698, 2021). "This suggests that NUDT1 regulates cell division, proliferation, and migration, which are critical for tumor recurrence and clinical outcomes." (PMID 32341205, 2020). "The level of NUDT1 expression correlated with tumor grade, stage, size, differentiation, degree of vascular invasion, overall survival (OS), and disease-free survival (DFS) in HCC patients." (PMID 32341205, 2020). "NUDT1 is involved in oxidative stress protective mechanism necessary for tumor cells survival since tumors produce large amounts of oxidants." (PMID 29202775, 2017). "The top candidate metabolic drivers were PYCRL, ALG3 and NUDT1, which were correlated in at least seven of the ten tumour types." (PMID 27358048, 2016). "Removal of oxidized nucleotides by NUDT1 (also known as MTH1) might relieve tumor cells from replicative stress and thereby represent a vulnerability and an ideal target for anticancer compounds." (PMID 38493213, 2024). "One study confirmed that NUDT1 could facilitate the mutation of the RAS, thereby damaging the tumor DNA structure." (PMID 37848855, 2023). "In solid tumours, hypoxia is common and may alter the response of tumour cells to NUDT1 inhibitors, which have an impact on redox signaling." (PMID 37086071, 2023). "Next, we highlighted the NUDT1 expression in each tumor's stages." (PMID 35096203, 2022). "In addition, the correlation between NUDT1 expression and immune checkpoint marker implicates the role of NUDT1 in regulating tumor immunology in ccRCC." (PMID 36606241, 2022). "In addition, high expression of NUDT1 in tumor tissues will lead to worse overall survival (OS) and progression-free survival (PFS) of colorectal cancer patients." (PMID 36606241, 2022). "Subsequently, immunohistochemistry based on subcutaneous transplanted tumours also showed that the expression level of the corresponding antioxidant enzymes decreased significantly after knocking down NUDT1, and the tumour malignant index KI67 also decreased significantly." (PMID 34841698, 2021). "The oxidant driving factors in ccRCC may be the reason for the toxic effect of NUDT1 inhibition on tumour cells." (PMID 34841698, 2021). "MiR-485-5p acts as a tumor suppressor by targeting NUDT1 in GC." (PMID 29075149, 2017). "The consistent overexpression of NUDT1 across tumor samples and its association with poor prognosis, alongside its regulatory relationship with HIF2α and impact on key cellular pathways, strongly position MTH1 (the protein product of NUDT1) as a promising biomarker candidate for RCC." (PMID 40507948, 2025).
tumor (continued). "As expected, Nudt1 knockout significantly increased the expression of phosphorylated γH2AX in sympathetic ganglia associated with elevation of cleaved-Caspase 3, corroborating that NUDT1 deletion caused overwhelming DNA damages and cell death in MYCN-driven tumor contexts in vivo." (PMID 38493213, 2024). "Moreover, the NUDT1 was found to be upregulated in KIRC tumor samples." (PMID 35096203, 2022). "NUDT1 levels correlated positively with AFP expression, tumor grade and size and degree of vascular invasion." (PMID 40507948, 2025). "miR-145 directly targets EGFR (Epidermal Growth Factor Receptor) and NUDT1 (Nudix Hydrolase 1), thereby inhibiting downstream oncogenic signaling pathways, mainly EGFR/PI3K/AKT, and suppressing tumor growth." (PMID 41465462, 2025). "MutT homologue-1 (MTH1), also called NUDT1, is a member of the Nudix family that maintains the genomic integrity and viability of tumor cells." (PMID 39272872, 2024). "We constructed a prognostic nomogram with NUDT1 expression, AFP levels, vascular invasion, Child–Pugh classification, age, sex, AJCC staging, and tumor differentiation as variables." (PMID 32341205, 2020). "In the present study, we show that high NUDT1 expression strongly correlates with advanced primary tumor, tumor grade, degree of vascular invasion, and AJCC tumor stage." (PMID 32341205, 2020). "We constructed a prognostic nomogram including NUDT1 expression, and clinical factors, such as, AFP levels, vascular invasion, Child–Pugh classification, age, sex, AJCC staging, and tumor differentiation." (PMID 32341205, 2020). "NUDT1 protein expression positively correlated with the TNM stage (P =0.024), tumor size (P = 0.040), and tumor differentiation (P=0.031)." (PMID 32341205, 2020). "NUDT1 mRNA expression positively correlates with the level of AFP expression (P = 0.000), pathological tumor stage (P = 0.038), tumor size (P=0.031), tumor grade (P = 0.000), and the degree of vascular invasion (P = 0.005)." (PMID 32341205, 2020). "On the basis of these results, NUDT1 (MTH1) was also significantly overexpressed in these reported tumor tissues, compared to those with the corresponding non-tumor tissues." (PMID 31164636, 2019). "MiR-145 had been well described to be involved in tumor invasion and progression by targeting c-Myc, AEG-1, EGFR, NUDT1 and OCT4 in LAC15, 16, 17, and acknowledged to be a putative tumor-suppressor miRNA." (PMID 26582602, 2015). "To summarize, in non-small cell lung cancer (NSCLC), the overexpression of the NUDT1 gene was detected in the vast majority of analyzed tumor tissues, along with elevated levels of MTH1 protein relative to non-neoplastic samples." (PMID 40507948, 2025). "Collectively, these findings robustly support the hypothesis that NUDT1 plays a pivotal role in RCC pathogenesis through its involvement in oxidative stress defense, immune regulation, and tumor cell survival mechanisms." (PMID 40507948, 2025). "Moreover, we observed elevated p-S121 NUDT1 levels in MYC(N) high tumor cells and tumor samples in comparison to those with low MYC(N) expression." (PMID 38493213, 2024). "Despite low expression of NUDT1 in tumor tissues, NUDT1 was not detectable in normal ones." (PMID 35784919, 2022).
NUDT1 also shares sentences with these, for which no sentence is quoted: colon carcinoma (6 papers); non-small cell lung carcinoma (6); osteosarcoma (6); brain tumors (4); esophageal squamous cell carcinoma (4); renal cell carcinoma (4); liver cancer (3); mesothelioma (3); acute lymphoblastic leukemia (2); adenocarcinoma (2); cervical cancer (2); Clear Cell Renal Cell Carcinoma (2); cognitive deficit (2); gastric tumor (2); head and neck cancer (2); infection (2); lymph node metastasis (2); neurodegenerative disease (2); psoriasis (2); small cell lung carcinoma (2); abortion (1); acute myeloid leukemia (1); allergic asthma (1); Alzheimer disease (1); autoimmune disease (1); B-cell lymphoma (1); bipolar disorder (1); brain cancer (1); breast tumors (1); central nervous system disorder (1).
A further 44 diseases each share a sentence with NUDT1 in 1 paper.